BCL6 (BCL6 transcription repressor)
Diseases named in the same sentence as BCL6 in open-access papers (continued):
Sharing a sentence is not in itself a finding about the gene and the disease.
bullous pemphigoid (1 paper, 2023). Bullous pemphigoid (BP) is the most common form of autoimmune bullous dermatosis. "HDAC4 is also associated with B-cell lymphoma 6 (BCL6), a repressor protein essential for germinal center B cells and T follicular helper cells (Tfh), known to be increased in the blood of bullous pemphigoid patients." (PMID 38255677, 2023).
Chronic colitis (1 paper, 2020). A chronic inflammatory disease of the large intestine (colon, cecum and rectum). "SSP effectively treated chronic colitis, regulated the balance between Tfh10, Tfh17 and T follicular regulatory cells, while SSP increased the Blimp-1 level, inhibited expressions of Bcl-6, T-cell costimulator, programmed death (PD)-1 and PD-ligand 1 on the surface of Tfh cells." (PMID 32581849, 2020).
chronic pancreatitis (1 paper, 2013). A chronic inflammatory process causing damage and fibrosis of the pancreatic parenchyma. "Interestingly, PPARβ/δ expression was also elevated while mRNA expression of the transcriptional repressor BCL-6 was almost 3-fold lower in tumor samples compared with those from chronic pancreatitis patients." (PMID 23737761, 2013).
coloboma (1 paper, 2020). An abnormality in which a part of a structure in one or both eyes is missing.
colorectal adenoma (1 paper, 2015). An adenoma that arises from the colon or rectum. "Most interestingly, in the Gaspar Colon colorectal adenoma dataset Bcl6 expression was significantly positively correlated with MAPK9, MAP2K4 and Yes1, and negatively with Dlg2, relative to normal intestinal mucosa." (PMID 26187947, 2015).
coronary artery disease (1 paper, 2022). "A study has demonstrated their pro-atherogenic roles in a Bcl6 mouse model, and proved their existence in the plasma of human subjects with coronary artery disease." (PMID 35534881, 2022).
coronary atherosclerosis (1 paper, 2023). Atherosclerosis of the coronary vasculature. "Moreover, RPS3A, BCL6, and S100B play a critical role in coronary atherosclerosis." (PMID 37316908, 2023).
dementia (1 paper, 2019). Loss of intellectual abilities interfering with an individual's social and occupational functions. "DS dementia strongly correlates with overexpression of miR-155 on chromosome 21 with concomitant reduction of multiple CNS-functional targets, including BACH1, CoREST1, Cyclin D1, BCL6, BCL10, BIM, and SAPK4." (PMID 31824553, 2019). "Recent evidence suggests that DS dementia strongly correlates with overexpression of miR-155 on chromosome 21 with concomitant reduction of multiple CNS-functional targets, including BACH1, CoREST1, Cyclin D1, BCL6, BCL10, BIM, and SAPK4." (PMID 31824553, 2019).
ductal invasive breast carcinoma (1 paper, 2018). "Although BCL6 expression has been demonstrated to increase in high grade of ductal invasive breast carcinoma patients, many aspects of the molecular mechanisms linked to its expression remain to be elucidated." (PMID 29854311, 2018).
endometrioid carcinoma (1 paper, 2020). "The LINC00152 and BCL6 protein were expressed predominantly in the nucleus in the ovarian high-grade serous and endometrioid carcinoma tissues; however, the sensitive immunofluorescence showed that there were still residual amounts of LINC00152 and BCL6 proteins localized in the cytoplasm." (PMID 33282727, 2020).
endometritis (1 paper, 2024). An acute or chronic, usually bacterial infectious process affecting the endometrium. "Of these, 48 (78.7%) consented for endometrial biopsy to rule out endometritis and test for BCL6 and/or SIRT1." (PMID 38999962, 2024).
falciparum malaria (1 paper, 2013). "Other important components of THαβ immune response included up-regulation of HMOX1, FAS, BCL6, TNFRSF10A, and MIP1α were noted in Griffiths’ research, which studied the peripheral blood leukocytes from Kenyan children with acute falciparum malaria." (PMID 24188121, 2013).
fibrosis (1 paper, 2025). the formation of excess fibrous connective tissue in an organ or tissue in a reparative or reactive process. "Recent research has unveiled a contributory role of BCL6 in fostering cardiac fibrosis through the TGF-β1/Smads pathway, in addition to safeguarding against ischemic myocardial injury." (PMID 40066352, 2025).
gastrointestinal stromal tumor (1 paper, 2024). "BCL6 was induced by imatinib in gastrointestinal stromal tumor (GIST)." (PMID 39456751, 2024).
Graves disease (1 paper, 2023). Graves' disease is an autoimmune disorder that leads to overactivity of the thyroid gland (hyperthyroidism).It is caused by an abnormal immune system response that causes the thyroid gland to produce too much thyroid hormones. "miR-346 directly targets Bcl-6 to promote Tfh cell differentiation in the pathogenesis of Graves’ disease, whereas Bcl-6 binds to the miR-31 promoter to repress its transcription, leading to the release of CD40L and SAP, which contribute to Tfh function." (PMID 38264670, 2023).
HIV-1 infection (1 paper, 2015). The type species of lentivirus and the etiologic agent of acquired immunodeficiency syndrome (AIDS). "We further confirmed the phenotype of TFR by determining expression of the transcription factors Bcl-6 and Blimp-1, and evaluated the effects of ex vivo HIV-1 infection on their expression." (PMID 26482032, 2015).
HTLV infection (1 paper, 2012). "Thus, the high expression of BCL6 in HTLV infected cells may contribute to the silencing of viral gene expression and to the long clinical latency associated with HTLV infection." (PMID 22726420, 2012).
hypertrophic cardiomyopathy (1 paper, 2023). A condition in which the myocardium is hypertrophied without an obvious cause. "Additionally, the study identified potential candidate genes, such as COL1A2 and BCL6, which interact with PPP2R3A and are also believed to play a role in the progression of myocardial infarction and hypertrophic cardiomyopathy or in tumor development." (PMID 37868783, 2023).
inflammatory bowel disease (1 paper, 2020). A spectrum of small and large bowel inflammatory diseases of unknown etiology. "The T follicular helper T (Tfh) cells play a significant role in the pathogenesis of inflammatory bowel disease (IBD), which is regulated by the Bcl-6/Blimp-1 pathway." (PMID 32581849, 2020).
intrahepatic cholangiocarcinoma (1 paper, 2025). A carcinoma that arises from the intrahepatic bile duct epithelium in any site of the intrahepatic biliary tree. "Notably, Saikosaponin-a (SSA), a triterpenoid saponin from Radix Bupleuri, was shown to enhance chemosensitivity in intrahepatic cholangiocarcinoma by targeting the p-AKT/BCL-6/ABCA1 axis." (PMID 41181146, 2025).
knee osteoarthritis (1 paper, 2024). "Specifically, cinnamaldehyde may affect knee osteoarthritis by regulating apoptosis-related genes such as ZFAND5, BCL6, ELL2, FOSL2, MARCKS, and SGCD." (PMID 39376659, 2024).
leiomyoma (1 paper, 2025). A well-circumscribed benign smooth muscle neoplasm characterized by the presence of spindle cells with cigar-shaped nuclei, interlacing fascicles, and a whorled pattern. "Although there is limited evidence linking BCL6 expression to leiomyomas, some authors have shown higher mRNA expression of BCL6 in leiomyomas, compared to normal myometrium." (PMID 39903727, 2025). "In contrast, one study reported BCL6 protein overexpression in only one out of nine leiomyoma samples using a subjective scoring system." (PMID 39903727, 2025).
lipid metabolism disorders (1 paper, 2022). "Mice lacking Bcl6 showed multiple characteristics of lipid metabolism disorders, accompanied by adipose tissue dysplasia." (PMID 36313453, 2022).
lipodystrophy (1 paper, 2014). A congenital or acquired disorder characterized by abnormal loss or redistribution of the adipose tissue in the body. "Future studies may reveal these and other features contributing to the lipodystrophy in Bcl6 KO mice." (PMID 24892698, 2014). "The marked reduction of adipose tissue mass in Bcl6 KO mice, which can be considered a lipodystrophy, raises the idea that Bcl6 may contribute to adipogenesis, the process during which preadipocytes differentiate into metabolically functional, lipid-storing adipocytes." (PMID 24892698, 2014).
liver diseases (1 paper, 2022). "The persistently affected genes Lama5, Gtse1, Fabp4, and Bcl6 possess the potential to be therapeutic targets for liver disease induced by AFB1." (PMID 35783385, 2022). "The persistently affected Lama5, Gtse1, Fabp4 and Bcl6 gene can be potential target genes for the treatment of AFB1 induced liver diseases, but their effectiveness needs to be further explored in experiments." (PMID 35783385, 2022).
Lyme disease (1 paper, 2022). Lyme disease (named after the towns in the USA where the disease was first identified) is a bacterial infection caused by Borrelia burgdorferi.
malignant rhabdoid tumors (1 paper, 2021). "Additionally, combing LDC0000167 with the BRD4 inhibitors-JQ1 or iBET-762 against malignant rhabdoid tumors, down-regulated the anti-apoptotic genes MCL-1, BCL-6 and BTG1 as well as MYC and inhibited cell-proliferation and tumor growth in vitro and in vivo." (PMID 34062779, 2021).
malnutrition (1 paper, 2021). Inadequate nutrition resulting from poor diet, malabsorption, or abnormal nutrient distribution. "The results of subgroup analysis showed that a significant deterioration of OS in GCB, CD5 positive, and BCL-6 positive groups with malnutrition identified by PNI." (PMID 34729103, 2021).
mesenchymal tumors (1 paper, 2022). "Specifically, BCL6, was previously found highly expressed in mesenchymal tumors, including GISTs, with a mechanism unrelated to rearrangements in the BCL6 gene." (PMID 36293105, 2022).
muscular atrophy (1 paper, 2022). The loss of muscle tissue due to inactivity or disease. "Our results indicated that miRNA-10a-5p and the target gene BCL6 have potential application value in the treatment of rhabdomyosarcoma and muscular atrophy." (PMID 36076940, 2022).
muscular dystrophies (1 paper, 2026). "Although transcriptome-wide studies have shown BCL6 dysregulation in muscular dystrophies, investigations into its endogenous roles in muscle biology remain scarce." (PMID 41985672, 2026).
myeloid leukemia (1 paper, 2020). A clonal proliferation of myeloid cells and their precursors in the bone marrow, peripheral blood, and spleen. "However, a role for BCL6 in myeloid leukemia has not been reported." (PMID 33024076, 2020).
myeloid tumors (1 paper, 2023). "What is noteworthy is that MYC rearrangement is found not only in BL and HGBL with MYC and BCL2 and/or BCL6 rearrangements but also in DLBCL, FL, PBL, B-LBL/ALL, and even in myeloid tumors." (PMID 37182167, 2023).
nodal marginal zone lymphoma (1 paper, 2024). "Pediatric nodal marginal zone lymphoma was ruled out as it typically shows marginal zone differentiation and does not express the germinal center markers (CD10 and BCL6 positivity) observed in our case." (PMID 39840177, 2024).
non-alcoholic steatohepatitis (1 paper, 2024). "BCL6 has also been shown to suppress non-alcoholic steatohepatitis (NASH)-induced liver injury associated with hepatic cancer." (PMID 39456751, 2024).
OFCD syndrome (1 paper, 2022). "Collectively, our findings suggest that BCOR mutation-induced ZFPM2 regulation via BCL6 possibly contributes to hyperactive root formation in OFCD syndrome." (PMID 35957990, 2022). "In this study, we show that a BCOR mutation induced ZFPM2 regulation via BCL6, subsequently regulating ALP expression and cellular proliferation and possibly contributing to hyperactive root formation in the OFCD syndrome." (PMID 35957990, 2022).
oral cancers (1 paper, 2019). "The inhibition of miR-155 under melatonin administration was significant, as miR-155 is known to modulate additional pathways of cellular proliferation and apoptosis in oral cancers through p27Kip1 and BCL6/cyclin D2." (PMID 31052365, 2019).
oropharyngeal cancer (1 paper, 2024). Carcinoma, predominantly squamous cell, arising from the epithelial cells of the oropharynx. "The overexpression of BCL6 in HNC fosters tumor growth and metastasis, with BCL6 expression and neutrophil infiltration serving as significant prognostic indicators in HPV-related oropharyngeal cancer." (PMID 39628997, 2024).
osteomyelitis (1 paper, 2019). An acute or chronic inflammation of the bone and its structures due to infection with pyogenic bacteria. "The present study aimed to elucidate the NFATc1 and BCL6 mediated osteoclastic regulation and activity in MRONJ (BP) compared to osteoradionecrosis (ORN) and osteomyelitis (OM) and normal jaw bone." (PMID 30832685, 2019).
otitis (1 paper, 2021). "The levels of expression of BLIMP-1 and XBP1 were significantly lower in patients who were prone than those who were not prone to otitis, whereas expression of BCL6 and PAX5 tended to be higher in the otitis-prone group." (PMID 33801155, 2021).
otitis media (1 paper, 2021). Inflammation of the anatomical structures of the middle ear, which is most often caused by an infectious process. "B cell leukemia/lymphoma-6 (Bcl-6) and paired box gene 5 (Pax-5) suppress antibody production, whereas B lymphocyte inducer of maturation program 1 (Blimp-1) and X-box binding protein 1 (XBP-1) promote antibody production during immune responses in patients with otitis media." (PMID 33801155, 2021).
ovarian lymphoma (1 paper, 2022). A lymphoma that affects the ovary. "DLBCL comprised the largest proportion of primary ovarian lymphoma; and according to the most frequently used Hans classification, DLBCL could be categorized into two subtypes: germinal center B-cell-like (GCB) and non-GCB, based on the immune indexes CD10, BCL-6, and MUM-1." (PMID 35477468, 2022).
pituitary adenomas (1 paper, 2014). "BCL6 is essential in pituitary adenoma due to interactions with several factors, including STAT3, IL-6 and JUNB." (PMID 25360166, 2014).
polyp (1 paper, 2016). A usually exophytic mass attached to the underlying tissue by a broad base or a thin stalk. "The transcription factor analysis showed that IL-21-expressing CD8+ T cells in polyp tissues expressed higher levels of Bcl-6 and T-bet than did IL-21−CD8+ T cells, and polyp CD8+ T cells were capable of promoting IgG generation by purified polyp B cells." (PMID 27468819, 2016). "IL-21-expressing CD8+ T cells in polyp tissues expressed higher CXCR5, PD-1, and ICOS levels than cells in control tissues and showed significantly higher T-bet and Bcl-6 expression levels compared with IL-21−CD8+ T cells." (PMID 27468819, 2016). "Some of the IL-21-producing CD8+ T cells in polyp tissues co-expressed IFN-γ, CXCR5, PD-1, ICOS, T-bet and Bcl-6, which display the T follicular helper (Tfh) cell functionality." (PMID 27468819, 2016).
prediabetes (1 paper, 2023). "In this study the mRNA expression of BCL6 was found to be upregulated in patients associated with prediabetes disease." (PMID 37457235, 2023).
primary cutaneous lymphoma (1 paper, 2023). Cutaneous lymphoma is a heterogeneous entity with respect to its clinical and pathological features, evolutive profile, prognosis, molecular etiology and response to therapy. "Primary cutaneous diffuse large B-cell lymphoma, leg type (PCDLBCL-LT), is a rare and aggressive variant of primary cutaneous lymphoma that typically expresses B cells as well as MUM1/IRF4, BCL2, and FOXP1, whereas BCL6 may be present or undetectable." (PMID 37754668, 2023).
prostate lymphoma (1 paper, 2018). A rare non-Hodgkin or Hodgkin lymphoma that arises from the prostate gland. "CK, CD3, CD21, CD23, CD10, Bcl6, MUM1, Blc2, CD5, CyclinD1 and Ki-67 are the most common immunohistochemical combinations for prostate lymphoma." (PMID 29308052, 2018).
psoriasis (1 paper, 2020). An autoimmune condition characterized by red, well-delineated plaques with silvery scales that are usually on the extensor surfaces and scalp. "In this respect, it is interesting that in both psoriasis and SLE the LL37-specific Th17-cells do exist and express Ror-ɣt but only in SLE, and not in psoriasis, they can express the TFH-markers Bcl-6 and high IL-21, at polyclonal and clonal levels." (PMID 32245990, 2020).
pulmonary fibrosis (1 paper, 2022). Chronic progressive interstitial lung disorder characterized by the replacement of the lung tissue by connective tissue, leading to progressive dyspnea, respiratory failure, or right heart failure. "Similarly, we found increased expression of BCL6 in the datasets of mouse (GSE2250) and human (GSE40839) lung fibrosis models." (PMID 35484551, 2022).
sarcoidosis (1 paper, 2024). Sarcoidosis is a multisystemic disorder of unknown cause characterized by the formation of immune granulomas in involved organs. "(e) Finally, sarcoidosis-associated B cells expressed MS4A1 (also known as CD20), FCER2 (also known as CD23), BCL6, and AICDA, which are all markers of late-stage differentiated B cells in mature TLSs." (PMID 39225100, 2024). "Finally, sarcoidosis-affected skin was enriched in B cells that expressed CDA and BCL6, 2 genes typically induced during late-stage changes in germinal center differentiation and isotype switching." (PMID 39225100, 2024).
schistosomiasis (1 paper, 2017). An infectious disease caused by parasitic trematodes of the genus Schistosoma that colonize human blood vessels and release eggs that can cause granulomatous reactions leading to acute (swimmer's itch or acute schistosomiasis syndrome) or chronic disease. "Furthermore, we also found that Bcl-6 instructed Tfh development to commence early in murine schistosomiasis." (PMID 29192177, 2017). "Using the mice model of schistosomiasis, the present study also indicated that Bcl-6+CD4+ cells would express higher CXCR5 of Tfh marker molecules than Bcl-6−CD4+ cell, the ability of Bcl-6 to up-regulate the expression of CXCR5 was strengthened in mice following S. japonicum infection." (PMID 29192177, 2017).
seminoma (1 paper, 2024). A radiosensitive malignant germ cell tumor found in the testis (especially undescended), and extragonadal sites (anterior mediastinum and pineal gland). "BCL6+ cells were only found in seminomas containing follicular-like structures (FLS)." (PMID 38649788, 2024). "Importantly, a high density of cells expressing Treg-specific markers CD25 and FOXP3, or Tfh-specific markers CXCR5 and BCL6, were found mainly in seminoma." (PMID 38649788, 2024). "CXCR5 + BCL6+ Tfh cells were identified in all TGCT locations with the highest percentage (0.05–2.40%, median of 0.30%) in the seminoma “Tumor”." (PMID 38649788, 2024).
transitional cell carcinoma (1 paper, 2016). A malignant neoplasm arising from the transitional epithelium, usually affecting the urinary bladder, ureter, or renal pelvis. "Our study is consistent with a report indicating that Bcl-6 expression was significantly increased in transitional cell carcinoma of the urinary bladder, kidney and urethra." (PMID 27237631, 2016). "In addition, Bcl-6 protein expression, determined by immunohistochemical staining, correlated positively with grades 1 and 2 but not grade 3 of transitional cell carcinomas." (PMID 27237631, 2016).